PRMT1 (protein arginine methyltransferase 1)
Diseases named in the same sentence as PRMT1 in open-access papers (continued):
Sharing a sentence is not in itself a finding about the gene and the disease.
breast carcinoma (continued). "For example, novel PRMT1 circRNAs in breast cancer and BCL2L12 circRNAs in colorectal cancer share this feature, where several nucleotides at the exons forming the back-splice junction are identical." (PMID 37888203, 2023). "A recent paper discovered that TAMs secrete IL-6 in the TME to stimulate protein arginine methyltransferase 1 (PRMT1)-mediated meR342-EZH2 formation in order to stabilize the enhancer of Zeste Homolog 2 (EZH2) in breast cancer cells." (PMID 35805995, 2022). "Here, mostly based on proximity ligation assays (PLAs) and ChIP-qPCRs, we report that PRMT1 interacts within this repressive complex and targets uPR-dependent promoters in hormone-free T47D breast cancer cells." (PMID 36076907, 2022). "In previous studies on the relationship between PRMTs family and breast cancer, PRMT1 is verified overexpressed in breast cancer tumor samples, and its expression degree is related to tumor grade." (PMID 35311114, 2022). "Here, we found that protein arginine methyltransferase 1 (PRMT1) is highly expressed in all breast cancer subtypes." (PMID 35053470, 2022). "It is evident that the regulatory pathways in which PRMT1 circular transcripts are involved, impacting breast cancer development and progression, are elaborate and intertwining, rendering the function of this gene even more complex than previously thought." (PMID 35885916, 2022). "In unstimulated T47D breast cancer cells, PRMT1 interacts and functions alongside uPR and its partners to target endogenous progesterone-responsive promoters." (PMID 36076907, 2022). "PRMT1 is also overexpressed in breast cancer tumor samples, and its expression degree is related to tumor grade." (PMID 35311114, 2022). "PRMT1 is proven to contribute to the pathogenesis of many types of cancer and is predominantly characterized as an early catalyst of breast cancer." (PMID 35885916, 2022). "Here, we examined the expression of PRMT1 in the different breast cancer subtypes, evaluated its potential as a therapeutic target, and explored its function in TNBC cells." (PMID 35053470, 2022). "PRMT1 depletion decreases cell survival by inducing DNA damage and apoptosis in various breast cancer cell lines." (PMID 35053470, 2022). "Although histone methylation by PRMT1 is largely involved in breast cancer development and metastasis, the effect of circular transcripts deriving from this gene has not been examined." (PMID 35885916, 2022). "In particular, seven PRMT1 circRNAs can sponge miR-494-3p with a high probability score, which is proved to regulate the renewal of breast cancer stem cells, as well as to affect the survival of breast cancer patients." (PMID 35885916, 2022). "Data from the present research evidence the existence of novel splicing events and truncated exons in the sequence of the novel PRMT1 circRNAs, broadening our understanding of alternative splicing events of this gene, in the context of breast cancer." (PMID 35885916, 2022). "The critical involvement of PRMT1 in the tumorigenesis and progression of breast cancer, as well as the preservation of stem cell-like features in breast cancer cells, is considered a very intriguing and complex process." (PMID 35885916, 2022). "Through the optimization of the PCR protocols that were implemented, qualitative expression analysis of the circRNAs that are produced from PRMT1 was performed in four breast cancer cell lines of distinct molecular subtypes." (PMID 35885916, 2022). "Taken together, our results suggest that PRMT1-mediated meR342-EZH2 plays a critical role in the cell cycle progression of breast cancer." (PMID 34775498, 2021). "Pearson’s correlation indicated that PRMT1 was significantly correlated with olaparib sensitivity in 44 breast cancer cell lines (r = 0.491, p < 0.001)." (PMID 34683150, 2021). "For instance, our previous study showed that overexpression of PRMT1 inhibits breast cancer cell senescence by increasing ZEB1 expression." (PMID 34775498, 2021).
breast carcinoma (continued). "We next tested the anti-cancer potency of PRMT1 inhibitor Fur in breast cancer cell lines and primary cancer cells." (PMID 34440533, 2021). "The relationship between PRMT1 expression and the clinicopathologic characteristics of breast cancer was further explored." (PMID 34440533, 2021). "PRMT1 facilitating cell cycle progression in breast cancer is likely dependent on PRMT1-mediated meR342-EZH2." (PMID 34775498, 2021). "To further determine the function of PRMT1, we established PRMT1 knockdown cell lines via lentiviral shRNA infection in breast cancer cells, MCF7 and MDA-MB-231." (PMID 34440533, 2021). "To identify the mechanism by which PRMT1 affects breast cancer cell proliferation and senescence, we analyzed the published RNA-seq dataset in PRMT1-knockdown MDA-MB-231 cells." (PMID 34440533, 2021). "The analysis of cancer vs. normal breast samples in TCGA database revealed that PRMT1 expression level was significantly elevated in breast cancer patients compared with the adjacent normal tissues." (PMID 34440533, 2021). "In summary, our results indicate that PRMT1-mediated meR342-EZH2 can enhance cell proliferation in breast cancer cells." (PMID 34775498, 2021). "We further analyzed the correlations between PRMT1 and sensitivities to 200 anticancer drugs in breast cancer cells." (PMID 34683150, 2021). "PRMT1-mediated meR342-EZH2 is able to enhance breast cancer cell migration and metastasis in vitro and in vivo." (PMID 34775498, 2021). "In breast cancer, overexpression of PRMT1 promotes tumor metastasis by modulating EZH2, and PRMT1 is associated with and prompts insulin-like growth factor I signaling in ER-positive breast cancer cells." (PMID 34683150, 2021). "Another interesting aspect is the key role of PRMT1 in the maintenance of stem-cell-like properties of breast cancer cells." (PMID 34833023, 2021). "Taken together, our data suggest that PRMT1-mediated meR342-EZH2 inhibits SUZ12 binding with EZH2 by preventing AMPKα1-mediated pT311-EZH2 in breast cancer." (PMID 34775498, 2021). "We found that protein arginine methyl transferase 1 (PRMT1) was significantly correlated with therapeutic sensitivity to the PARP inhibitor olaparib in breast cancer cells." (PMID 34683150, 2021). "We also analyzed the expression patterns of PRMT subtypes in patients with breast cancer, and the results validated that PRMT1, PRMT2 and PRMT4 were elevated in patients with TNBC compared with levels in those with non-TNBC." (PMID 34683150, 2021). "PRMT1 also regulates EMT in breast cancer cells while CARM1/PRMT4 promotes breast cancer metastasis by methylating arginine residue R1064 of BAF155, a chromatin remodeling factor." (PMID 33440687, 2021). "Subsequent analysis of the transcriptome from the breast cancer cohort in TCGA_BRCA indicated that PRMT1 was elevated in breast tumor tissues compared with normal tissues." (PMID 34683150, 2021). "Supporting this, the addition of MG132 only marginally increased PRMT1 ubiquitylation, whilst protein levels of PRMT1 in two different breast cancer cell lines were unchanged after doxycycline-induced depletion or overexpression of USP11." (PMID 34728620, 2021). "We believe that a PRMT1-specific inhibitor in combination with metformin will be a promising therapeutic strategy to prevent breast cancer progression in patients." (PMID 34775498, 2021). "In this study, we demonstrated that PRMT1 catalyses EZH2-R342 methylation and is necessary for PRMT1 to promote cell proliferation in breast cancer in vitro and in vivo." (PMID 34775498, 2021). "The data showed that meR342-EZH2 was highly expressed in breast cancer patients with high PRMT1 expression, whereas pT311-EZH2 was expressed at low levels in breast cancer tissues with high PRMT1 expression." (PMID 34775498, 2021).
breast carcinoma (continued). "We also demonstrated that tumor-associated maceophages (TAMs) facilitate PRMT1-mediated R342-EZH2 ADMA methylation by secreting IL-6, which strengthens EZH2 protein stability and enhances breast cancer cells motility." (PMID 33308321, 2020). "Our study suggest that PRMT1 inhibitor is a promising clinical drug to decreasing breast cancer patients metastasis." (PMID 33308321, 2020). "Dysfunction of BRCA1-mediated DNA repair in PRMT1-silenced breast cancer cells was also evidenced by monitoring 53BP1 foci formation in irradiated cells." (PMID 32764667, 2020). "To understand the molecular mechanism by which IR induced PRMT1-dependent methylation of BRCA1 in breast cancer cells, we first analyzed the effect of IR on PRMT1 expression at both the protein and mRNA levels." (PMID 32764667, 2020). "Similar results were obtained from experiments carried out with a 4T1 murine breast cancer cell line in which PRMT1 was efficiently knocked out using CRISPR/Cas9." (PMID 32764667, 2020). "In MDA-MB-231 breast cancer cell line, the knockdown of PRMT1 accumulates cells in the G2/M phase and results in senescence." (PMID 30741995, 2019). "For example, RALY and SNW1 stimulate exon 2 inclusion in PRMT1, promoting breast cancer invasiveness and CDK12 promote alternative last exon splicing of DNA damage genes ATM and DNAJB6 thereby increasing migration and invasiveness of breast cancer cells." (PMID 31666932, 2019). "Previous reports have indicated that PRMT1 promoted the progression of a panel of cancers, such as gastric cancer and breast cancer, by increasing tumorigenicity and invasion potential." (PMID 31043582, 2019). "Significant changes in expression of PRMT1 have been observed in various cancer types, such as lung carcinoma, colon cancer, breast carcinoma, prostate and bladder cancer, gastric carcinomas, and gliomas." (PMID 31655611, 2019). "PRMT1 was identified as an important oncoprotein that is frequently overexpressed in many tumours, including breast cancer, lung cancer, and colon cancer." (PMID 31043582, 2019). "PRMT1 was reported to be upregulated in breast cancer, lung cancer and colon cancer and to promote the proliferation and transformation of cancer cells." (PMID 31043582, 2019). "PRMT1 has also been identified as a key regulator of the epithelial–mesenchymal transition in breast cancer." (PMID 29868478, 2018). "In HCC, as with colon and breast cancer, high expression of PRMT1 was significantly related to a poor prognosis, which was confirmed with the Korean cohort." (PMID 29383172, 2017). "Several papers have reported that PRMT1 expression is elevated in various types of cancer, including lung cancer, bladder cancer, breast cancer and acute myeloid leukemia, and that PRMT1 knockdown induces the suppression of cancer cell growth and metastasis." (PMID 29383172, 2017). "Results from this study first implicate that downregulation of PRMT1 with specific siRNAs induces senescence in breast cancer cells, as assessed by SA-β-gal staining." (PMID 26813495, 2016). "Arginine methyltransferase inhibitor 1 (AMI-1) was used to pharmacologically block PRMT1 in resistant breast cancer cells (MCF7/adr)." (PMID 26934120, 2016). "We also demonstrated that abrogation of PRMT1 expression in breast cancer cells abated metastasis in vivo in mouse model." (PMID 26813495, 2016). "Lastly, luciferase reporter gene and nude mice bearing resistant breast cancer xenografts were adopted to investigate the anti-tumor effect of PRMT1 inhibitors when combined with adriamycin." (PMID 26934120, 2016). "Taken together, these data indicate that silencing of PRMT1 can lead to the mitotic errors and trigger the senescence of breast cancer cells, as a result of the downregulation of G2/M genes." (PMID 26813495, 2016). "Meanwhile, knockdown of PRMT1 not only suppressed metastasis in vivo in mice, but also provoked cellular senescence in breast cancer cells." (PMID 26813495, 2016).
breast carcinoma (continued). "For instance, PRMT1-v2 is overexpressed in breast cancer cell lines and mammary tumors and its cytoplasmic localization is linked with its key role in cell survival and invasion of breast cancer cells." (PMID 27556302, 2016). "In current study, AMI-1 was used to pharmacologically block PRMT1 in adriamycin-resistant breast cancer cell line MCF7/adr." (PMID 26934120, 2016). "The subcellular localization of PRMT1 is highly consistent with PXR in resistant breast cancer cells, and the physical interaction exists between the two proteins." (PMID 26934120, 2016). "Upregulation of the protein is a feature of many types of human cancers, and high levels of PRMT1 mRNA have notably been reported in high grade breast cancers." (PMID 27556302, 2016). "To determine the correlation of PRMT1 expression level with the malignancy and metastasis of breast cancer cells, we first compared the PRMT1 level in normal mammary epithelial MCF10A cell and multiple breast cancer cell lines." (PMID 26813495, 2016). "To verify the in vitro observations, we investigated the effect of PRMT1 on the distant metastasis of breast cancer cells in vivo in nude mice." (PMID 26813495, 2016). "An interesting finding arising from this study is that, ectopic expression of PRMT1 was able to induce EMT, whereas suppression of PRMT1 provoked senescence in breast cancer cells." (PMID 26813495, 2016). "BRCA1 was found to be methylated by PRMT1 in breast cancer cell lines, as well as in breast tumor samples." (PMID 27556302, 2016). "Here we identified PRMT1 as a key regulator of the epithelial-mesenchymal transition (EMT) in breast cancer." (PMID 26813495, 2016). "We have previously shown that the alternatively spliced PRMT1 isoform, PRMT1v2, promotes breast cancer cell survival and invasion." (PMID 25605249, 2015). "Of note, the V2 isoform only comprises less than 5% of total PRMT1 level, but V2 is mainly responsible for oncogenic activities in colon and breast cancers." (PMID 26575292, 2015). "PRMT1 methylates ERα in breast cancer cells promoting its extranuclear signaling and its interaction with PI-3 kinase and Src." (PMID 25605249, 2015). "Additionally, PRMT1 can promote the proliferation of breast cancer cells by inhibiting the transcription and expression of p16 and p21." (PMID 39890802, 2025). "We investigated the expression levels of PRMT1 within the single-cell RNA sequencing cohorts BRCA-GSE143423 and BRCA-GSE150660, and the analysis of these datasets demonstrated that PRMT1 expression is predominantly localized in the malignant epithelial cells of breast cancer." (PMID 40927753, 2025). "In breast cancer, PRMT1-v2 is often overexpressed, promoting cellular invasiveness." (PMID 41204384, 2025). "Similarly, PRMT1 is frequently overexpressed in other tumor types, including breast cancer, where its dysregulation contributes to oncogenic signaling pathways and cellular transformation." (PMID 40791817, 2025). "In docetaxel-resistant breast cancer tissues, the expression of PRMT1 and PARP1 was increased." (PMID 40927753, 2025). "Besides its role in breast cancer, overexpression of PRMT1 also promotes the Wnt/β-catenin pathway in other types of cancer, such as gastric cancer." (PMID 40001488, 2025). "Furthermore, abrogation of PRMT1 drastically reduces cell growth by arresting the breast cancer cells in the G2/M phase, which leads to erroneous cell division and growth." (PMID 40001488, 2025). "Overexpression of PRMT1 has been detected in human breast cancer patients." (PMID 40001488, 2025). "Notably, PRMT1 v.2 is also demonstrated to augment the survival and invasive properties of breast cancer cells." (PMID 38911125, 2024). "PRMT1 v.1 and v.2 expression is significantly reduced in breast cancer." (PMID 38911125, 2024).
breast carcinoma (continued). "Moreover, we performed copy number variation (CNV) analysis for PRMT1 in the 11 breast cancer cell lines, based on the Cancer Cell Line Encyclopedia, in order to assess any correlation with the number of identified PRMT1 circRNAs." (PMID 37692475, 2024). "EZH2 R342 methylation by PRMT1 increases EMT of breast cancer cells." (PMID 37143582, 2023). "Similarly, another study illustrated that methylation of EZH2 by PRMT1 at R342 promoted breast cancer cell EMT, invasion, and metastasis, and high levels of EZH2 methylation was associated with poor clinical outcome in breast cancer patients." (PMID 37737256, 2023). "In this study, we combined customized PCR protocols and Sanger sequencing with extensive bioinformatics analysis to elucidate the expression pattern of PRMT1 circRNAs in four breast cancer cell lines and untangle the unique alternative splicing events that occur during the back-splicing process." (PMID 35885916, 2022). "Interestingly, PRMT1 was shown to be dramatically overexpressed in breast cancer, and patients with higher PRMT1 expression display a higher malignancy grade, in part through the activation of proliferation-related genes." (PMID 36076907, 2022). "PRMT1 interacts with the progesterone receptor in the nucleus of breast cancer cells." (PMID 35053470, 2022). "PRMT1 gene expression is substantially higher in breast tumor samples than in healthy breast tissues, and several studies evidence its role in regulating the metastatic potential of breast cancer, as well as therapy efficacy." (PMID 35885916, 2022). "In agreement with the pioneer study of Beato’s group, these results indicate that, in the absence of hormonal stimulation, PRMT1 takes part in the silencing of a subset of progestin-responsive genes encoding key cellular functions in breast cancer cells." (PMID 36076907, 2022). "However, PRMT1 can repress the transcriptional activity of C/EBPα by methylating it at R35, R156, and R165, which leads to rapid growth of breast cancer cells." (PMID 35941115, 2022). "In this study, we investigated the possible role of PRMT1 circRNAs in breast cancer cell lines." (PMID 35885916, 2022). "Interestingly, ZNF486 was reported to reliably predict the prognosis of breast cancer patients, rendering it a promising candidate for further investigation as a PRMT1 circRNAs target." (PMID 35885916, 2022). "Moreover, PRMT1-mediated EZH2-R342 methylation can increase breast cancer cell proliferation and enhance breast cancer tumorigenesis." (PMID 34775498, 2021). "This suggests that PRMT1-mediated meR342-EZH2 may promote breast cancer cell proliferation and tumorigenesis in vitro and in vivo." (PMID 34775498, 2021). "This suggested that EZH2 is required for PRMT1 to facilitate breast cancer cell proliferation." (PMID 34775498, 2021). "Here we revealed that EZH2 is necessary for PRMT1 to enhance breast cancer cell proliferation." (PMID 34775498, 2021). "Interestingly, we showed that PRMT1 also can enhance breast cancer cell proliferation after inhibiting BRCA1 or c-Myc functions by their specific inhibitor." (PMID 34775498, 2021). "In addition, PRMT1 depletion decreases the expression of a specific subset of progesterone-target genes, involved in breast cancer cell proliferation and migration." (PMID 34833023, 2021).